LILRB4 (leukocyte immunoglobulin like receptor B4)
Description:
Inhibitory receptor involved in the down-regulation of the immune response and the development of immune tolerance. Receptor for FN1. Receptor for apolipoprotein APOE. Receptor for ALCAM/CD166. Inhibits receptor-mediated phosphorylation of cellular proteins and mobilization of intracellular calcium ions. Inhibits FCGR1A/CD64-mediated monocyte activation by inducing phosphatase-mediated down-regulation of the phosphorylation of multiple proteins including LCK, SYK, LAT and ERK, leading to a reduction in TNF production. This inhibition of monocyte activation occurs at least in part via binding to FN1. Inhibits T cell proliferation, inducing anergy, suppressing the differentiation of IFNG-producing CD8+ cytotoxic T cells and enhancing the generation of CD8+ T suppressor cells. Induces up-regulation of CD86 on dendritic cells. Interferes with TNFRSF5-signaling and NF-kappa-B up-regulation.
Synonyms: B4; ILT-3; LIR-5; CD85k; ILT3; LIR5; HM18
Tractability: Antibody: UniProt places it where antibodies can reach, with high confidence; UniProt predicts a signal peptide or a membrane-spanning region; its Gene Ontology location is reachable by antibodies, with medium confidence.
Gene: Protein-coding gene on chromosome 19 (54,643,889 to 54,670,359, forward strand). Ensembl gene ENSG00000186818.
Subcellular location: Cell membrane
Pathways (Reactome):
Immune System: Immunoregulatory interactions between a Lymphoid and a non-Lymphoid cell
Gene Ontology:
Molecular function: apolipoprotein binding; fibronectin binding; protein binding; protein phosphatase binding; protein tyrosine kinase inhibitor activity; signaling receptor inhibitor activity; transmembrane receptor protein tyrosine kinase inhibitor activity; inhibitory MHC class I receptor activity
Biological process: Fc receptor mediated inhibitory signaling pathway; interleukin-10-mediated signaling pathway; negative regulation of activated T cell proliferation; negative regulation of canonical NF-kappaB signal transduction; negative regulation of chemokine production; negative regulation of cytokine production involved in inflammatory response; negative regulation of cytotoxic T cell differentiation; negative regulation of interleukin-1 beta production; negative regulation of interleukin-10 production; negative regulation of interleukin-2 production; negative regulation of interleukin-5 production; negative regulation of interleukin-6 production; negative regulation of intracellular signal transduction; negative regulation of IP-10 production; negative regulation of MAPK cascade; negative regulation of miRNA transcription; negative regulation of monocyte activation; negative regulation of osteoclast differentiation; negative regulation of protein localization to nucleus; negative regulation of T cell costimulation; negative regulation of T cell cytokine production; negative regulation of T cell proliferation; negative regulation of T cell receptor signaling pathway; negative regulation of tumor necrosis factor production; negative regulation of type II interferon production; and 8 more
Cellular component: cell surface; extracellular exosome; plasma membrane; cytoplasmic side of plasma membrane
Genetic constraint (gnomAD): Loss-of-function variants: 49 observed, 56.01 expected, observed/expected ratio (o/e) 0.87, 90% interval 0.69 to 1.11. The upper end of that interval is the gene's LOEUF score, 1.11, which puts it in group 4 of 6, group 1 being the genes least tolerant of losing a copy. Missense variants: 590 observed, 568.34 expected, observed/expected ratio (o/e) 1.04, 90% interval 0.97 to 1.11. Synonymous variants: 229 observed, 220.16 expected, observed/expected ratio (o/e) 1.04, 90% interval 0.93 to 1.16.
Homologues: Orthologues: chimpanzee LILRB4 (96% identical), macaque LILRB4 (67% identical), rat Pirb (45% identical), rat Lilrb3 (35% identical), rat Lilrb2 (30% identical), mouse Pira12 (29% identical), mouse Pira2 (29% identical), mouse Pira1 (29% identical), mouse Pira13 (29% identical), mouse Pirb (28% identical), mouse Lilra6 (27% identical), rat LOC134485274 (27% identical), and 3 more. Paralogues in human: LILRB1 (68% identical), LILRB3 (68% identical), LILRB2 (55% identical), LILRB5 (54% identical), LILRA6 (39% identical), LILRA2 (35% identical), LILRA4 (35% identical), LILRA1 (34% identical), LILRA5 (30% identical), KIR3DL1 (26% identical), KIR3DL3 (26% identical), KIR3DL2 (25% identical), and 13 more.
Diseases named in the same sentence as LILRB4 in open-access papers:
LILRB4 is named in the same sentence as 92 diseases in open-access papers, as found by Europe PMC text mining. Sharing a sentence is not in itself a finding about the gene and the disease. The quoted sentences say what the papers report.
leukemia (20 papers, 2017 to 2025). A malignant (clonal) hematologic disorder, involving hematopoietic stem cells and characterized by the presence of primitive or atypical myeloid or lymphoid cells in the bone marrow and the blood. "Earlier studies showed that LILRB4 regulates melanoma, multiple myeloma, and leukemia, via activation of STAT3 and inhibition of NF-κB." (PMID 41102383, 2025). "As in monocyte AML cells, LILRB4 (leukocyte immunoglobulin-like receptor B4), a marker for mononuclear leukemia, coordinates the tumor invasion pathway by mediating T cell suppression." (PMID 39975548, 2025). "FTO inhibition significantly decreased leukaemia stem cell self-renewal by abolishing the increase in LILRB4 expression and sensitized human AML cells to T-cell cytotoxicity." (PMID 36859310, 2023). "In vivo analysis further confirmed that targeting FTO/m6A/LILRB4 overcomes immune evasion in leukaemia." (PMID 36859310, 2023). "have shown that highly expressed FTO can inhibit the immune activity of T lymphocytes by increasing the expression of the immunosuppressive checkpoint molecule/gene “LILRB4”, thereby promoting the progression of leukemia stem cells." (PMID 37916161, 2023). "In leukaemia, tumour cells disable immune checkpoint blockade therapy through the LILRB4 signalling, and blocking LILRB4 can prevent the development and metastasis of tumour cells." (PMID 36748687, 2023). "From this perspective, prolonged inhibition of DOT1L seems to favor KMT2A-rearranged leukemia cells that completely lack PROM1/CD133 but do display LILRB4/CD85k and CD33 expression." (PMID 37740239, 2023). "Genetic depletion and pharmacological inhibition of FTO not only dramatically attenuated self-renewal of leukaemia stem cells, but also reprogrammed immune response by suppressing LILRB4 expression." (PMID 37875589, 2023). "In leukemia, inhibition of FTO attenuates the self-renewal of leukemia stem cells and suppresses immune checkpoint receptors, especially leukocyte immunoglobulin-like receptor B4 (LILRB4)." (PMID 35804965, 2022). "In a regular culture, LILRB4 overexpression significantly promoted the proliferation of leukemia cells compared with the control." (PMID 35771283, 2022). "Mechanistically, LILRB4 has been shown to support leukemia cell migration and suppress T cell activity via activation of the ApoE/LILRB4/SHP2/uPAR/arginase-1 signaling axis in M-AML cells." (PMID 35076022, 2022). "LILRB4 signaling in leukemia cells promotes T cell suppression and tumor infiltration." (PMID 39845086, 2024). "Furthermore, CS1 and CS2 inhibited the self-renewal of leukemia-initiating cells and suppress immune infiltration by decreasing LILRB4 mRNA stability." (PMID 37916161, 2023). "Genetic depletion or pharmacological inhibition of FTO dramatically attenuates leukemia stem/initiating cell self-renewal and reprograms immune responses by suppressing the expression of immune checkpoint genes such as leukocyte immunoglobulin-like receptor B4 (LILRB4)." (PMID 35296338, 2022). "Furthermore, recent data by Zhang and colleagues suggest that LILRB4 signaling in leukemia cells mediates T cell suppression and supports tumor cell dissemination to distal organs." (PMID 32870822, 2020). "Notably, in leukemia, inhibition or reduction of FTO expression blocks leukocyte immunoglobulin-like receptor B4, an immune checkpoint gene expression, inhibits the self-renewal ability of stem cells, while enhancing leukemia sensitivity to drugs and preventing the development of immune evasion." (PMID 39033180, 2024). "Moreover, FTO can also inhibit the expression of immune checkpoint genes, especially LILRB4, significantly weakening the self-renewal and reprogramming immune response of leukaemia stem cells/initiating cells, which has been proven to be an effective treatment strategy for AML." (PMID 39641872, 2024). "LILRB4 represents a compelling CAR T target in AML, due to its selective expression on both leukemia cells and HSCs." (PMID 40860159, 2025).
leukemia (continued). "Preclinically, LILRB4 STAR-T cells effectively eliminated LILRB4+ AML cells 358, with dual-epitope targeting demonstrating enhanced anti-leukemia activity in vivo." (PMID 40860159, 2025).
acute myeloid leukemia (14 papers, 2021 to 2025). Acute myeloid leukemia (AML) is a group of neoplasms arising from precursor cells committed to the myeloid cell-line differentiation. "As an immune checkpoint, LILRB4 deletion impedes acute myeloid leukaemia (AML) development by reversing the immunosuppressive microenvironment." (PMID 40576161, 2025). "We specifically examined the role of leukocyte immunoglobulin-like receptor 4a (LILRB4a or LILRB4), which is known to suppress immunity in acute myeloid leukemia (AML) and solid tumors." (PMID 41102383, 2025). "LILRB4 is highly expressed in acute myeloid leukemia and mediates T-cell suppression and infiltration." (PMID 38971897, 2024). "LILRB1 and LILRB4 expression, independently, are highly sensitive for monocytic differentiation in acute myeloid leukemia (M-AML)." (PMID 39696628, 2024). "ApoE has been identified as an extracellular binding protein of leukocyte immunoglobulin-like receptor B4 (LILRB4), and disruption of the LILRB4/apoE interaction blocks the development of acute myeloid leukemia." (PMID 37310025, 2023). "Our previous study reported that apoE activated LILRB4 signaling to mediate immune escape and extramedullary infiltration of acute myeloid leukemia (AML) by cell–cell independent manner." (PMID 38951916, 2024). "LILRB4 is a molecular marker of M4 and M5 acute myeloid leukemia (AML), which mediates the immune escape and extramedullary infiltrates of AML." (PMID 38951916, 2024). "Additionally, FTO has been identified as having an oncogenic role in multiple cancers, and it targets LILRB4 in acute myeloid leukemia (AML) cells." (PMID 38397424, 2024). "In more recent findings, LILRB4 was shown to bind CD166 (activated leukocyte adhesion molecule, ALCAM) and serum apolipoprotein E (APOE), which mediate tumor cell growth and acute myeloid leukemia, respectively." (PMID 38397424, 2024). "For example, in acute myeloid leukemia (AML), inhibiting the demethylase FTO can suppress the expression of immune checkpoint molecules PD-L1 and LILRB4, inducing T-cell cytotoxicity against tumor cells." (PMID 39726589, 2024). "Furthermore, in acute myeloid leukemia (AML), FTO inhibition can lead to downregulation of leukocyte immunoglobulin-like receptor subfamily B member 4 (LILRB4), render AML cells vulnerable to activated T cells, and simultaneously overcome hypomethylating agent (HMA)-induced immune evasion." (PMID 34988083, 2021).
autoimmune disease (11 papers, 2014 to 2025). A disorder resulting from loss of function or tissue destruction of an organ or multiple organs, arising from humoral or cellular immune responses of the individual to their own tissue constituents. "LILRB4 is associated with several diseases, including cancer, autoimmune diseases, chronic inflammation, infectious diseases, and transplantation 27–31." (PMID 38971897, 2024). "Lilrb4 is involved in immune responses and inflammatory processes associated with autoimmune diseases, infectious diseases, inflammation disorders, and cancers and is negatively regulated in immune cell activation." (PMID 38892016, 2024). "LILRB4 expression marks tolerogenic DCs and has been reported to be elevated in APCs of cancer patients and decreased in autoimmune diseases." (PMID 31849951, 2019). "Thus, LILRB4 has emerged as a key player in addressing autoimmune diseases, transplant tolerance induction, and other medical issues." (PMID 38397424, 2024). "Its ability to induce effector T cell dysfunction and promote T suppressor cell differentiation has been demonstrated, indicating the therapeutic potential of LILRB4 for modulating excessive immune responses, particularly in autoimmune diseases or the induction of transplant tolerance." (PMID 38397424, 2024). "Given that the activation of LILRB4 induces immune tolerance, it seems that LILRB4 signaling may well exert beneficial effects in autoimmune diseases, transplantation biology, and maternal–fetal interactions." (PMID 38954358, 2024). "The results show that LILRB4 and its derived recombinant protein LILRB4-Fc have strong immunosuppressive effects and play a key role in the treatment of autoimmune diseases, the induction of transplantation tolerance and the induction of maternal–fetal immune tolerance." (PMID 38397424, 2024). "In addition, LILRB4 can inhibit the activation of auxiliary T cells, inactivate activated effector cells and transform them into inhibitive T cells and regulatory T cells, and play an important role in transplant tolerance, hypersensitivity and autoimmune diseases, such as lupus erythematosus." (PMID 31138763, 2019). "Gene variants at the TSBP1-AS locus are strongly associated with the levels of complement component 4 (C4), C2/LILRB4 protein level ratio, IGA glomerulonephritis, BMI, lipoprotein levels, and with many autoimmune diseases including celiac disease (GWAS catalog)." (PMID 40883722, 2025).
melanoma (8 papers, 2007 to 2025). A malignant, usually aggressive tumor composed of atypical, neoplastic melanocytes. "Studies have shown that the immunosuppressive capacity of MDSCs is adjusted by the inhibitory molecule leukocyte immunoglobulin-like receptor B4 (LILRB4) in patients with non-small-cell lung cancer and in mice with melanoma occurring as subcutaneous tumors." (PMID 37461040, 2023). "We tested a variety of murine solid tumor models for the role of LILRB4, which showed that LILRB4 is a potential target in solid tumors such as melanoma." (PMID 33974041, 2021). "Soluble LILRB4 has been found in the serum of pancreatic carcinoma, colorectal carcinoma, and melanoma patients, and T cell responses are increased in vitro upon treatment with anti-LILRB4 antibody." (PMID 33974041, 2021). "Our NanoString gene expression data showed relatively high LILRB4 expression in human melanoma in comparison to other inhibitory receptors." (PMID 33974041, 2021). "Soluble LILRB4 has been found in the serum of patients with melanoma, colorectal cancer and pancreatic cancer." (PMID 31138763, 2019). "LILRB4 was expressed in 50% multiple myeloma (17/34), 8% prostate cancer (4/50), 4.5% hepatocellular carcinoma (5/110) and 11.9% melanoma (10/84)." (PMID 38951916, 2024). "Similarly, we also found LILRB4 protein expression on tumor-infiltrating CD45+ cells in melanoma patients." (PMID 33974041, 2021).
multiple myeloma (8 papers, 2022 to 2025). "High expression of LILRB4 has also been associated with worse outcomes in multiple myeloma (MM)." (PMID 39696628, 2024). "LILRB4 promotes tumour progression by activating the NF‐κB pathway in multiple myeloma and lung adenocarcinoma." (PMID 40576161, 2025). "Relapsed or refractory multiple myeloma (RRMM) expresses higher levels of LILRB4 than newly diagnosed multiple myeloma (NDMM)." (PMID 41417876, 2025). "In multiple myeloma, LILRB4 activates the STAT3‐PFKFB1 pathway to promote cancer cell proliferation." (PMID 40576161, 2025). "Concordant with its expression in certain B lineage cells, it was reported that LILRB4 is expressed in myeloma cells." (PMID 38951916, 2024). "Here, we found that LILRB4 was significantly positively correlated with bone injury in multiple myeloma." (PMID 38951916, 2024). "The patient’s imaging data showed that the higher the expression level of LILRB4, the more serious the bone lesion in patients with multiple myeloma." (PMID 38951916, 2024). "Next, human LILRB4 was overexpressed in mouse myeloma cell line J558, and the CM was used to treat the primary mouse bone marrow mononuclear cells." (PMID 38951916, 2024). "The surface proteomic analysis of multiple myeloma identified LILRB4 as a potential immunotherapeutic target." (PMID 38951916, 2024). "In this study, we used immunohistochemistry to comprehensively analyze the expression of LILRB4 in various tumor tissue arrays, and found that LILRB4 was highly expressed in multiple myeloma samples." (PMID 38951916, 2024). "Unexpectedly, LILRB4 was expressed in 50% of multiple myeloma samples, and flow cytometry further validated this result." (PMID 38951916, 2024). "Here, we revealed that leukocyte immunoglobulin-like receptor B4 (LILRB4) was highly expressed in multiple myeloma cell lines and patient samples and that the expression of LILRB4 was adversely correlated with the overall survival of MM patients." (PMID 39025844, 2024). "We comprehensively analyzed the expression of LILRB4 in various tumor tissue arrays, and found that LILRB4 was highly expressed in multiple myeloma samples." (PMID 38951916, 2024). "Our data supported that LILRB4 signal pathway promoted the differentiation and mature of osteoclasts by secreting RELT, and LILRB4 had the potential to be a new target for the treatment of multiple myeloma." (PMID 38951916, 2024). "To determine the effect of myeloma-expressing LILRB4 on osteoblasts, we employed the CM of LILRB4-WT or -KO cells to treat MC3T3-E1 cell line (mouse embryonic calvarial fibroblasts)." (PMID 38951916, 2024). "To clarify the mechanism by which LILRB4 promotes bone lesion of multiple myeloma, we used cytokine arrays to identify the differentially expressed cytokines in the CM from LILRB4-WT and -KO cells." (PMID 38951916, 2024). "RNA-seq, cytokine array, qPCR, the activity of luciferase, Co-IP and western blotting were used to clarify the mechanism by which LILRB4 mediated bone damage in multiple myeloma." (PMID 38951916, 2024). "Our data revealed a new function of LILRB4, elucidated a new mechanism by which multiple myeloma promotes bone damage." (PMID 38951916, 2024). "Next, we collected bone marrow samples from 5 cases of multiple myeloma, and found that higher level of LILRB4 in CD45−/CD38+ multiple myeloma cells seems to correspond to a tendency towards more RELT level in serum." (PMID 38951916, 2024). "Although LILRB4 was also expressed in several other solid tumors, the level was lower, therefore, we focused on and explored the relationship between LILRB4 and multiple myeloma." (PMID 38951916, 2024). "LILRB4 breaks the balance between osteoclasts and osteoblasts, resulting in more severe bone damage in the multiple myeloma mouse model." (PMID 38951916, 2024). "LILRB4 was detected in 55.56% multiple myeloma samples (5/9)." (PMID 38951916, 2024).